TH (tyrosine hydroxylase)
Diseases named in the same sentence as TH in open-access papers (continued):
Sharing a sentence is not in itself a finding about the gene and the disease.
colorectal cancer (2 papers, 2020 to 2023). A primary or metastatic malignant neoplasm that affects the colon or rectum. "In the case of gastric and colorectal cancer, stem cells differentiate and acquire diverse phenotypes, mainly of autonomic neurons expressing VAChT (a marker of parasympathetic neurons), or TH (Tyrosine hydroxylase, characteristic of sympathetic neurons)." (PMID 32555170, 2020).
Developmental delay (2 papers, 2018 to 2022).
endometriosis (2 papers, 2015 to 2025). The growth of functional endometrial tissue in anatomic sites outside the uterine body. "NFDs of Anti-TH (+) endometriosis-associated sympathetic nerve of peritoneal endometriosis (p<0.001) and deep endometriosis of uterosacral ligament (p<0.001) were significantly lower than NFDs of para-endometriotic sympathetic nerve." (PMID 26720585, 2015). "NFD of Anti-TH (+) endometriosis-associated sympathetic nerve of peritoneal endometriosis (EASN-PEM) was significantly lower than NFD of para-endometriotic sympathetic nerve of peritoneal endometriosis (PESN-PEM) (p<0.001)." (PMID 26720585, 2015). "NFD of Anti-TH (+) endometriosis-associated sympathetic nerve of uterosacral ligament endometriosis (EASN-USL-EM) was also lower than NFD of para-endometriotic sympathetic nerve of uterosacral ligament endometriosis (PESN-USL-EM) (p<0.001)." (PMID 26720585, 2015). "In deep infiltrating endometriosis, 20% of HRH1-positive nerves colocalized with substance P, and 40% showed colocalization with both tyrosine hydroxylase and VIP." (PMID 41516088, 2025).
Glucose intolerance (2 papers, 2022 to 2023). Glucose intolerance (GI) can be defined as dysglycemia that comprises both prediabetes and diabetes. "Specifically, the increase of TH neurons within area postrema significantly correlates with the development of glucose intolerance, which is in line with the selective control by area postrema of vagal neurons innervating the pancreas." (PMID 36387998, 2022).
Hearing Loss (2 papers, 2007 to 2015). "As TH autoantibodies were found only in two patients, not correlating to a hearing disability, TH does not appear to be an autoantigen connected to the sensorineural hearing loss seen in Turner syndrome." (PMID 18088406, 2007).
Hydrocephalus (2 papers, 2022). Hydrocephalus is an active distension of the ventricular system of the brain resulting from inadequate passage of CSF from its point of production within the cerebral ventricles to its point of absorption into the systemic circulation. "The increase in the levels of the enzyme TH, frequently used as a validated method to identify noradrenergic LC neurons, has never been reported in the kaolin-induced hydrocephalus model." (PMID 35409327, 2022). "In the present study, striatal TH level was not affected by hydrocephalus, in accord with earlier reports that striatal dopamine level remained steady in experimental hydrocephalic rats and rabbits." (PMID 36437472, 2022). "Both Western blotting and immunohistochemical staining show that hydrocephalus did not alter the striatal TH expression." (PMID 36437472, 2022). "Hydrocephalus altered type 1 (DR1) and 2 (DR2) dopamine receptor expressions without affecting tyrosine hydroxylase level." (PMID 36437472, 2022).
hyperhomocysteinemia (2 papers, 2023 to 2025). A serious metabolic condition caused by mutations in the MTHFR gene, medications, or nutritional deficiency. "Hyperhomocysteinemia reduces tyrosine hydroxylase (TH) activity, leading to the degeneration of dopaminergic neurons and the progression of PD." (PMID 40137172, 2025). "Therefore, hyperhomocysteinemia-induced depletion of TH may not involve in the development but only in the progression of PD through the degeneration of dopaminergic neurons with secondary deficiency of TH in PD." (PMID 37074484, 2023).
Hyperphenylalaninemia (2 papers, 2014 to 2025). "The clinical picture of patient number 6 pointed to l-dopa responsive dystonia without hyperphenylalaninemia, which may occur in autosomal dominant GTPCH I deficiency, sepiapterin reductase (SR) deficiency, or in tyrosine hydroxylase (TH) deficiency." (PMID 24949445, 2014).
lentivirus infection (2 papers, 2020 to 2022). Virus diseases caused by the Lentivirus genus. "Together, these data showed that the lentivirus infections and overexpression of TH, AADC, and GCH1 did not raise any additional adverse effects or safety concerns." (PMID 36550118, 2022).
metastatic disease (2 papers, 2019 to 2022). "Diagnostic TH mRNA levels and CTC counts are typically higher in patients with more advanced metastatic disease and in patients with high-risk disease, as observed in other solid malignancies." (PMID 31088252, 2019). "This protocol led to an increase in sensitivity of TH mRNA detection by RT-qPCR from 58% to 90% and has since been implemented by the same group for MRD detection in patients with metastatic disease enrolled on the international phase 3 HR-NBL-1/SIOPEN trial." (PMID 31088252, 2019).
microcephaly (2 papers, 2018 to 2022). A congenital or acquired developmental disorder in which the circumference of the head is smaller than normal for the person's age and sex.
Myocardial fibrosis (2 papers, 2020 to 2021). "Also, the cardiac histopathology, myocardial oxidative stress markers (malondialdehyde (MDA), glutathione (GSH) and CAT) and norepinephrine (NE), myocardial fibrosis, the expression of caspase-3, TGF-β, TNF-α, and tyrosine hydroxylase (TH) in myocardial tissues were measured." (PMID 32106580, 2020).
neuroendocrine neoplasm (2 papers, 2018 to 2019). Endocrine tumors, also referred to as neuroendocrine tumors (NETs), are defined by a common phenotype which is characterized by the expression of general markers (neuron specific enolase, chromogranin, synaptophysin) and hormone secretion products. "Our results identify, for the first time, immunoreactivity of TH in mammalian (human) endothelial cells in a neuroendocrine neoplasm." (PMID 30199552, 2018).
ovarian carcinoma (2 papers, 2022 to 2024). A malignant neoplasm originating from the surface ovarian epithelium. "This neuronal or epithelial signature of ovarian carcinomas is raised from a rare cell type found in regular (non-tumoral) ovarian tissues which have a particular phenotype expressing Tyrosine hydroxylase, ChgA, the paraneoplastic protein PNMA1 and KRT80." (PMID 39592661, 2024).
phenylketonuria (2 papers, 2021 to 2022). Phenylketonuria (PKU) is the most common inborn error of amino acid metabolism and is characterized by mild to severe mental disability in untreated patients. "Due to the structural homology within the AAAHs, the effect of mutations causing TH enzyme defect may also be predicted on the PAH structure by analogy from the multiple mutations in PAH observed in patients with phenylketonuria (PKU)." (PMID 34834538, 2021).
polycystic ovary (2 papers, 2019 to 2024). "Injection of propranolol restored the tyrosine hydroxylase and ovarian dopamine β-hydroxylase levels in rats with polycystic ovary syndrome induction." (PMID 31744506, 2019). "Propranolol (PROP), an adrenergic receptor antagonist, could prevent isoproterenol-induced polycystic ovary, enhancing the ovulation rate and reducing tyrosine hydroxylase and dopamine β-hydroxylase concentrations in the ovarian tissue." (PMID 38512862, 2024).
prostate carcinoma (2 papers, 2003 to 2022). A carcinoma that arises from epithelial cells of the prostate gland. "We examined the associations between prostate cancer with polymorphisms of the insulin gene (INS) and its neighbouring genes, tyrosine-hydroxylase and IGF-II (TH and IGF2)." (PMID 12610512, 2003).
renal fibrosis (2 papers, 2019 to 2021). A final common manifestation of a wide variety of chronic kidney diseases characterized by glomerulosclerosis and tubulointerstitial fibrosis. "Empagliflozin administration caused a reduction in blood pressure in CsA-treated rats and showed a protective effect on CsA nephropathy by decreasing renal fibrosis, type I and type IV collagen expression, macrophage infiltration and tyrosine hydroxylase expression." (PMID 33760995, 2021). "In our experimental conditions, CsA administration caused an increase in blood pressure and renal fibrosis at glomerular and tubulo-interstitial area, but not at perivascular level, and an increase in renal inflammatory cell infiltration and tyrosine hydroxylase expression." (PMID 33760995, 2021).
respiratory depression (2 papers, 2014 to 2018). A decrease in ventilation secondary to impaired signals from the central nervous system. "In about half of the trials, TH-VHLKO mice exposed to hypoxia also showed a transient loss of consciousness and marked respiratory depression (Fig8A, red line)." (PMID 25385837, 2014). "However, TH is transiently expressed in other cell types during development, and it is evident that central respiratory depression can also be triggered by myogenic mechanisms that impact blood supply to the brain." (PMID 29928235, 2018).
rheumatoid arthritis (2 papers, 2014 to 2018). A chronic, systemic autoimmune disorder characterized by inflammation in the synovial membranes and articular surfaces. "In previous studies, newly appearing tyrosine hydroxylase-positive (TH+) catecholamine-producing cells have been detected in synovial tissue of rheumatoid arthritis (RA) and osteoarthritis (OA) patients." (PMID 29941879, 2018). "Changes in the density of sympathetic nerve fibers, which are characterized by tyrosine-hydroxylase (TH) or neuropeptide Y (NPY) or both, in synovial tissue contribute to rheumatoid arthritis (RA)." (PMID 25789373, 2014).
sexual dysfunction (2 papers, 2019). Disturbances in sexual desire and the psychophysiologic changes that characterize the sexual response cycle and cause marked distress and interpersonal difficulty. "We hypothesize that if the dopaminergic system is involved in sexual dysfunction caused by SSRIs, different antidepressant treatments will differentially modify TH immunoreactivity." (PMID 30678046, 2019). "The differential effects of paroxetine and agomelatine on the TH immunoreactivity and dopaminergic systems may partly explain the impact that the tested treatments have on sexual function, including the high frequency of sexual dysfunction in paroxetine-treated patients." (PMID 30678046, 2019).
sleep disorder (2 papers, 2015 to 2018). A change from the patient's baseline sleeping pattern, in the hours slept and/or an alteration/dysfunction in the stages of sleep. "Increased TH and norepinephrine levels led to the suppression of GABAergic VLPO neurons and consequently sleep disorders." (PMID 25801728, 2015).
teratoma (2 papers, 2008 to 2023). A non-seminomatous germ cell tumor characterized by the presence of various tissues which correspond to the different germinal layers (endoderm, mesoderm, and ectoderm). "When these in vitro differentiated neuronal cells were transplanted into CsA-treated recipients, tyrosine hydroxylase (TH)-positive neurites were present in the grafts suggesting a better integration of transplanted cells, however, now teratomas occurred in 2 of 15 animals." (PMID 18612432, 2008).
thyroid cancer (2 papers, 2023 to 2025). "In addition, this may be in relation to what has been reported in humans harboring variants in genes implicated in TH synthesis (NIS, TG, TPO, and SLC26A4); thyroid goiter with dyshormonogenesis may develop thyroid cancer later in life." (PMID 37964961, 2023).
adenoma (1 paper, 2021). A neoplasm arising from the epithelium. "Pathology and immunohistochemistry revealed a right adrenal tyrosine hydroxylase–positive PHEO and CYP11B2-positive adenoma." (PMID 34258494, 2021).
age (1 paper, 2024). A temporal measurement of the time period elapsed since an identifiable point in the life cycle of an organism. "Given that TH + neurons in the DMV may indirectly influence the withdrawal of cholinergic tone to the gut, which can lead to age-related gastrointestinal muscle atrophy, we hypothesized that neuron loss in the DMV could be linked to the observed changes in GTT." (PMID 38291230, 2024).
albinism (1 paper, 2020). A congenital disorder characterized by partial or complete absence of melanin pigment in the eyes, hair, or skin. "For example, mutation of tyrosine hydroxylase in the silkworm Bombyx mori causes albinism in the eyes, eggs, and wings." (PMID 32511225, 2020).
Arthritis (1 paper, 2018). Inflammation of a joint. "During RA progression and in the collagen type II model of arthritis, the loss of catecholaminergic tyrosine hydroxylase-positive (TH+) sympathetic nerve fibers occurs and, concomitantly, TH+ single cells with anti-inflammatory character appear in inflamed synovium." (PMID 29941879, 2018).
autoimmune hepatitis (1 paper, 2022). Hepatitis caused by autoantibodies. "Microbially deficient mice exhibited markedly reduced tyrosine hydroxylase (TH; the rate‐limiting enzyme for dopamine synthesis) mRNA in the gut, resulting in increased interferon‐gamma production, and exacerbation of autoimmune hepatitis." (PMID 34734461, 2022).
Autoimmunity (1 paper, 2022). The occurrence of an immune reaction against the organism's own cells or tissues. "Early studies reported the presence of nine HHV-8 ORF gene products associated with autoimmunity and shared significant homology with human cellular proteins, including the HHV-8 TH and dihydrofolate reductase (DHFR)." (PMID 36422613, 2022).
autonomic dysfunction (1 paper, 2025). "Immunofluorescence staining revealed that autonomic dysfunction in AR mice was ameliorated by minocycline, as evidenced by the up-regulation of TH and NPY and down-regulation of ChAT and VIP in the nasal mucosa." (PMID 41019284, 2025). "Immunofluorescence staining revealed that autonomic dysfunction in AR mice was ameliorated by IL-4 NAb, as evidenced by the up-regulation of TH and NPY and down-regulation of ChAT and VIP in the nose." (PMID 41019284, 2025).
brain tumors (1 paper, 2021). "In response to tibial loading, the levels of TH and dopamine were elevated in the brain and the serum, respectively, and loading-driven regulation of dopamine synthesis in the brain was associated with the inhibition of the growth of brain tumors." (PMID 34031366, 2021). "The results revealed that loading the tibia with elevated levels of tyrosine hydroxylase, a rate-limiting enzyme in dopamine synthesis, markedly reduced the progression of the brain tumors." (PMID 34031366, 2021).
cholangiocarcinoma (1 paper, 2023). A carcinoma that arises from the intrahepatic biliary tree (intrahepatic cholangiocarcinoma) or from the junction, or adjacent to the junction, of the right and left hepatic ducts (hilar cholangiocarcinoma). "TH, IGDCC3, RAD51AP2, and MUC2 are genes that were identified by WGCNA and are related to the clinical prognosis and survival of cholangiocarcinoma, but they have already been reported." (PMID 36979826, 2023).
Chorea (1 paper, 2022). Chorea (Greek for 'dance') refers to widespread arrhythmic involuntary movements of a forcible, jerky and restless fashion. "In contrast, a mildly impaired but independent gait pattern was commonly observed in patients with drug‐responsive neurotransmitters defects (GCH1, DHPR, SPR, TH, and PTPS), nonprogressive chorea (NKX2." (PMID 36054588, 2022).
Cirrhosis (1 paper, 2024). A chronic disorder of the liver in which liver tissue becomes scarred and is partially replaced by regenerative nodules and fibrotic tissue resulting in loss of liver function. "Furthermore, negative correlation was seen between the levels of TH protein and the tumor size, tumor number, the level of AFP, as well as cirrhosis." (PMID 38610044, 2024).
cognitive (1 paper, 2025). "In the PD-like mouse model, CAR-A was effectively activated, which ameliorated α-syn pathology, created a healthy microenvironment for neurons, restored dopaminergic neurons as well as TH and dopamine levels, and ameliorated motor and cognitive deficits." (PMID 41261395, 2025).
cognitive decline (1 paper, 2025). "At the molecular level, a significant loss of noradrenergic neurons in the LC was documented in AD, correlating with cognitive decline, as evidenced by mRNA expression for tyrosine hydroxylase (TH), α2A-AR, and NET, along with morphometric analysis." (PMID 39331291, 2025).
deficiencies (1 paper, 2015). "The prevalence of inherited monoamine metabolism disorders (autosomal dominant GTPCH, TH, DHPR and PTPS deficiencies) was 1.3% (4 out of 150 patients), which is similar compared to a previous study reporting 1.5% prevalence." (PMID 25758715, 2015).
Down syndrome (1 paper, 2015). "Quantification revealed a significant reduction in TH immunoreactivity in the Down syndrome tissues compared with controls (P=0.01 for spleen, P=0.026 for pancreas, t-test, n=3 each for Down syndrome and normal donor tissues)." (PMID 26658127, 2015). "Notably, we observed a significant reduction in the amount of TH/neurofilament-double-positive axons in Down syndrome tissues." (PMID 26658127, 2015). "We observed a trend towards decreased neurofilament immunoreactivity in the Down syndrome spleen and pancreas, although these deficits were not as severe as the decreases in TH immunoreactivity, and were not statistically different from control tissues." (PMID 26658127, 2015).
drug dependence (1 paper, 2010). "Our findings, together with previous studies, make it plausible that caffeine through adenosine A2A receptor-mediated phosphorylation of TH at Ser31, results in the dopaminergic neuroadaptations related to the treatment of PD and mechanism of drug dependence/addiction." (PMID 20074377, 2010).
Dysarthria (1 paper, 2022). Dysarthric speech is a general description referring to a neurological speech disorder characterized by poor articulation.
ependymoma (1 paper, 2019). A WHO grade II, slow growing tumor of children and young adults, usually located intraventricularly. "Furthermore, increased uptake of TH in cells treated with both T4 and TTR probably involves a T4 complex with TTR, as well as passive diffusion of T4, allowing for greater cell uptake than can be accomplished by diffusion only, which is consistent with observations in human ependymoma cells." (PMID 31817149, 2019).
experimental autoimmune encephalomyelitis (1 paper, 2021). An autoimmune demyelinating disease of the central nervous system that is produced experimentally in animals by the injection of homogenized brain or spinal cord in Freund's adjuvant. "It was demonstrated that Nr4a1 directly suppresses the gene expression level of tyrosine hydroxylase (TH), the rate‐limiting enzyme for norepinephrine (NE) production in macrophages which enzyme protects mice from experimental autoimmune encephalomyelitis (EAE)." (PMID 34358410, 2021).
Gaucher disease (1 paper, 2023). Gaucher disease (GD) is a lysosomal storage disorder encompassing three main forms (types 1, 2 and 3), a fetal form and a variant with cardiac involvement (Gaucher disease - ophthalmoplegia - cardiovascular calcification or Gaucher-like disease). "Biallelic TH and GBA variants were identified as the genetic cause of DRD and Gaucher’s disease." (PMID 37198191, 2023).